RPLP0 (ribosomal protein lateral stalk subunit P0)
Diseases named in the same sentence as RPLP0 in open-access papers (continued):
Sharing a sentence is not in itself a finding about the gene and the disease.
lung adenocarcinoma (1 paper, 2023). A carcinoma that arises from the lung and is characterized by the presence of malignant glandular epithelial cells. "The significant negative correlation for the ribosomal protein RPLP0 was corroborated by previous proteogenomic findings, in which ribosomal functions were found to be lowly correlated (an observation made not just in lung adenocarcinoma, but also in other cancer types)." (PMID 37511126, 2023).
lupus (1 paper, 2024). "Next, we hypothesized that the anti-TCP1 antibody could be a better biomarker than the anti-RPLP0, RPLP1, and RPLP2 antibodies, which were already known lupus autoantibodies." (PMID 39201300, 2024).
lymph node metastasis (1 paper, 2022). "On the contrary, patients with higher expression of RPLP0 usually exhibited distance metastasis, lymph node metastasis, and III/IV TNM stage." (PMID 35342398, 2022). "Additionally, in accordance with the results of miR-4731-5p, the level of RPLP0 was also notably related in lymph node metastasis, distance metastasis, and TNM stage, but no statistical difference was found between the expression of RPLP0 and age, gender, smoking, or tumor size." (PMID 35342398, 2022).
mesothelioma (1 paper, 2020). A usually malignant and aggressive neoplasm of the mesothelium which is often associated with exposure to asbestos. "Eleven asbestos-exposed controls were excluded from analyses because raw Ct values of GAS5 or RPLP0 in plasma were ≥ 35, resulted in 22 mesothelioma patients and 31 asbestos-exposed controls appropriate for analysis." (PMID 32435497, 2020).
mucinous ovarian tumors (1 paper, 2014). "With M values less than 1.5, HRPT1, RPL13A, ACTB, TBP, PBGD, and RPLP0 were recommended as a dependable normalizing combination for ovarian mucinous tumors." (PMID 24776823, 2014).
multinodular goiter (1 paper, 2019). Nodular goiter characterized by more than one discrete tissue mass. "The expression characteristics of 12 candidate reference genes (GAPDH, ACTB, HPRT1, TBP, B2M, PPIA, 18SrRNA, HMBS, GUSB, PGK1, RPLP0, and PGM1) were assessed by qRT-PCR in 45 thyroid tissue samples (15 papillary thyroid carcinoma, 15 paired normal tissues and 15 multinodular goiters)." (PMID 31645594, 2019).
nasal polyps (1 paper, 2018). "Our findings indicate that RPLP0 and RPLP1, either singly or in combination, are suitable for normalizing gene expression in nasal polyp and sinonasal tissues." (PMID 29371606, 2018).
ovarian serous tumor (1 paper, 2014). A benign, borderline, or malignant epithelial tumor of the ovary characterized by the presence of neoplastic epithelial cells that, in well differentiated tumors, resemble the epithelial cells of the fallopian tube and, in poorly differentiated tumors, show anaplastic features. "ACTB, PPIA, RPL13A, RPLP0, TBP, and B2M achieved high expression stability, which suggested that they were adequate for normalizing gene expression data among ovarian serous tumors." (PMID 24776823, 2014).
ovarian tumor (1 paper, 2014). "In conclusion, for an accurate gene expression assay in ovarian tumor tissues, homogeneous tissues as starting materials and normalization based on multiple validated reference genes, such as PPIA, RPLP0, ACTB, and TBP, are recommended." (PMID 24776823, 2014).
psoriasis (1 paper, 2014). An autoimmune condition characterized by red, well-delineated plaques with silvery scales that are usually on the extensor surfaces and scalp. "Furthermore, we confirmed that RPLP0 is not differentially expressed between psoriasis and controls by performing RNA sequencing on an independent set of psoriasis patients (18 lesional and 16 healthy skin controls), with a differential expression q-value of 0.123 (not significant)." (PMID 25224121, 2014).
Sepsis (1 paper, 2026). Sepsis is defined as life-threatening organ dysfunction caused by a dysregulated host response to infection. "Clinical qPCR validation confirmed that RPLP0 was significantly upregulated in sepsis patients, while CD52, RPS15A, and RPS18 were downregulated." (PMID 42291321, 2026).
tumor (20 papers, 2002 to 2025). "Proteomic profiling pointed to an association between RPLP0 up-regulation and cancer in several tumor cells, which is involved in mRNA translation." (PMID 27832777, 2016). "3.Exploring RPLP0-tumor stroma interactions: Study how RPLP0 interacts with stromal components such as cancer-associated fibroblasts and the extracellular matrix." (PMID 40777041, 2025). "In vitro mechanistic studies: Perform co-culture experiments of tumor cells with immune cells to determine the impact of RPLP0 on immune cell function." (PMID 40777041, 2025). "Through in vivo mouse experiments, siRNA interference, and ELISA, we demonstrated that RPLP0 knockdown in tumors and anti-PD-1 combinational treatment remarkably inhibited tumor growth and improved anti-tumor immunity." (PMID 40777041, 2025). "The result indicated that the combination of Rplp0 knockdown and anti-PD-1 treatment prominently suppressed tumor growth and prolonged survival of mice compared to siRplp0 or immunotherapy monotherapy." (PMID 40777041, 2025). "We observed that RPLP0 ranked extremely high in the number of times it was selected, even in the case of mixed tumor factors, which suggests that it is a robust biomarker." (PMID 40777041, 2025). "Also, conduct transcriptomic and proteomic analyses of RPLP0-knocked-down tumor cells to identify downstream effector molecules and pathways." (PMID 40777041, 2025). "Through enzyme-linked immunosorbent assay (ELISA), we found Rplp0 knockdown and immunotherapy combination remarkably augmented the IFN-γ and TNF-α levels in serum, which implies combinational treatment potentiated the anti-tumor immunity in mice." (PMID 40777041, 2025). "For instance, RPLP0 might affect the recruitment or function of immunosuppressive cells like MDSCs or Tregs, which are known to suppress anti-tumor immune responses." (PMID 40777041, 2025). "Concordantly, the RPLP0 protein expression profile in pan-cancer and immunohistochemistry images from the Human Protein Atlas database also demonstrated the elevated protein expression of RPLP0 in tumor tissues." (PMID 40777041, 2025). "We found that RPLP0 is highly expressed in tumor tissues and RPLP0 may regulate immune cell infiltration and activity in the TME." (PMID 40777041, 2025). "Thus, the findings demonstrated that the upregulated level of miR-4731-5p restrained NSCLC tumor growth by suppressing RPLP0 at the mRNA level." (PMID 35342398, 2022). "coli), RPLP0 (tumor progression, invasion, metastasis), RPS5, RPL9, RPS14, RPS2, RPL3, and RPL23." (PMID 34445327, 2021). "The presence of the RheoSwitch construct in the B16-RS cells enabled us to amplify and detect the RheoActivator element, which served as a tumor cell-specific marker, and was normalized to the expression of the 60S acidic ribosomal protein P0 (RPLP0), used as a house-keeping gene." (PMID 34830742, 2021). "Different pattern occurs for RG pair selection, since only RPL13 + RPLP0 selected by the GeNorm algorithm fulfils statistical criteria; therefore, for matched tumor-control-metastasized ccRCC samples (group IV) RPL13 + RPLP0 pair may be considered for normalization in gene expression studies." (PMID 25225161, 2014). "To directly compare general safe-harbour with tumour-specific knock-in, we performed co-culture experiments using IFNG-expressing SK-N-AS cells with integrations at AAVS1 or the tumour-specific RPLP0 locus." (PMID 41366257, 2025). "In parallel, tumour-secreted IFNG significantly inhibited M2-like macrophage polarization with comparable effects between AAVS1 and RPLP0 targeting, but a tendency toward dose dependency when comparing pre-sort to post-enrichment conditions." (PMID 41366257, 2025). "Most importantly, we characterized RPLP0 as an important regulator of NHEJ-mediated DSB repair and tumor radioresistance." (PMID 35974014, 2022).
tumor (continued). "Here, we discovered that the over-regulation of miR-4731-5p resulted in the low expression of RPLP0, leading to the retardation of NSCLC cell viability and invasion, and consequently inhibited tumor growth." (PMID 35342398, 2022). "The analysis showed nearly parallel expression to whole-tissue from the same tumor using the 4-group reference genes for ER+ IBC of TBP, RPLP0, PUM1 and ACTB, as observed by a Pearson correlation of 0.992." (PMID 18211679, 2008). "RPL4, RPLP0, and RPS6 are closely related to tumor growth and cell cycle control; this relationship indicates that they may contribute to the transcriptomic stability and survival of TICs." (PMID 40862733, 2025). "The combination of RPLP0 knockdown and anti-PD-1 treatment resulted in significantly suppressed tumor growth and prolonged survival in mice, accompanied by elevated levels of IFN-γ and TNF-α in serum samples, indicating enhanced anti-tumor immunity." (PMID 40777041, 2025). "RPLP0 interacts with GCIP to activate cyclin D1, thereby promoting tumor cell proliferation." (PMID 35974014, 2022). "We then hypothesized that NONO/RPLP0 may enhance tumor radioresistance." (PMID 35974014, 2022). "Radiation-induced NONO/RPLP0 complex binds to DSB and promotes DNA-PK autophosphorylation at T2609, leading to tumor radioresistance." (PMID 35974014, 2022). "Compared with tumor tissues from patients sensitive to radiochemotherapy (TRG0, tumor regression grades 0), both NONO and RPLP0 proteins were highly expressed in that from resistant patients (TRG3)." (PMID 35974014, 2022). "Together, these data suggest that IR-induced NONO/RPLP0 complex promotes DSB repair and tumor radioresistance by binding to damaged DNA and enhancing the phosphorylation of DNA-PK at T2609." (PMID 35974014, 2022). "Upon irradiation, NONO and RPLP0 are recruited to the damaged DNA end to increase DNA-PK phosphorylation at T2609, thereby enhancing NHEJ-mediated DSB repair and inducing tumor cell radioresistance." (PMID 35974014, 2022). "Four GPCRs were also over-expressed to a significant level within all three (WNT, SHH, Non-WNT/SHH) categorized tumor groups (FZD2, RPLP0, EDG4 and F2R)." (PMID 24252460, 2013). "In short, we discovered that miR-4731-5p and RPLP0 dysregulated NSCLC tissues and cell lines, which are involved in lymph node metastasis, distance metastasis, and III/IV TNM stage, with no relation to age, gender, smoking, or tumor size." (PMID 35342398, 2022). "Consistently, RPLP0 silencing significantly inhibited radiation-induced DNA-PK autophosphorylation at T2609 in tumor cells, which photocopied RPLP0 silencing, indicating that the NONO/RPLP0 complex may promote NHEJ by enhancing DNA-PK autophosphorylation at T2609." (PMID 35974014, 2022).
cancer (19 papers, 2012 to 2025). A tumor composed of atypical neoplastic, often pleomorphic cells that invade other tissues. "Since RPLP0 showed prominent expression in these cancers in pan-cancer analysis, and was frequently selected in IMvigor210 cohort screening." (PMID 40777041, 2025). "When a model was determined to be suitable for pan-cancer, there was always a ribosomal protein RPLP0, which ranked high in the number of times being selected in high-frequency LASSO screening in IMvigor210 cohorts." (PMID 40777041, 2025). "High expression levels of RPLP0 have been detected in many tumors, and depletion of RPLP0 can lead to apoptosis and cell cycle arrest in many cancer cells." (PMID 39110356, 2024). "The quantitative analysis of the gene expression involves five reference genes (ACTB, TFRC, GAPDH, GUSB, and RPLP0) and 16 cancer-related genes." (PMID 36042999, 2022). "Conversely, depletion of RPLP0 leads to apoptosis and cell cycle arrest in cancer cells." (PMID 35974014, 2022). "In addition, a recent report showed that RPLP0 was up-regulated in patients with the most common types of cancer, indicating that the expression level of RPLP0 could be useful as a prognostic marker in tumors." (PMID 27832777, 2016). "Here, we characterized RPLP0 as a NONO-interacting protein, and their association was significantly enhanced by X-ray irradiation, indicating that RPLP0 may function as a transductor that activates NONO-associated DNA repair components upon X-ray-induced DNA damage in cancer cells." (PMID 35974014, 2022). "The potential reference genes GAPDH, HPRT1, and RPLP0 were measured in all samples from NSCLC patients and cancer-free controls." (PMID 24313945, 2013). "For the Test Cancer BioChip, the negative controls employed included non-targeting, ACTB, GUSB, GAPDH, RPLP0, TFRC and cyclophilin siRNA as well as no siRNA." (PMID 23049944, 2012). "Additionally, the TCGA database showed that RPLP0 and NONO were highly expressed in a variety of cancer types, and survival analysis confirmed that high expression of RPLP0 and NONO was associated with an inferior prognosis of cancer patients." (PMID 35974014, 2022). "Interestingly, we observed that GAPDH, GUSB, IPO8, RPL13, RPL32, and UBC genes, as well as RPLP0 + TBP, RPL13 + RPL32, RPL13 + RPLP0, and ACTB + TBP RG pairs, were the only assays whose expression did not depend (P > 0.05) on cancer progression." (PMID 25225161, 2014).
infection (7 papers, 2017 to 2025). The state of being infected such as from the introduction of a foreign agent such as serum, vaccine, antigenic substance or organism. "Gene expression was monitored at multiple time post-infection (3, 6, 12, 16, 24, and 30 h), normalized to RPLP0 mRNA, and compared to both control (uninfected) samples and between MOI conditions." (PMID 41157617, 2025). "Using qRT-PCR, these researchers showed that this reduction was vhs dependent based on two sets of genes that exhibited either high (COL6A2, MMP3, and MMP1) or low (GAPDH, ACTB, and RPLP0) reduction in total RNA levels in WT infection." (PMID 33148793, 2021). "We saw a similar decrease in Pol II levels at the promoter with both antibodies as well as a decrease in the Rplp0 gene body Pol II occupancy with the antibody recognizing the Rpb1 N-terminus upon MHV68 infection." (PMID 32032393, 2020). "Among these proteins, 60 S acidic ribosomal protein P0 (RPLP0) was detected and showed significant changes in the early stages of infection by PRV in Madin-Darby bovine kidney cells." (PMID 28374783, 2017). "Indeed, the M4 promoter was repressed to a similar degree as host Fus and Rplp0 promoters during infection with WT MHV68 but not the mRNA decay-deficient MHV68 R443I at 24hpi." (PMID 32032393, 2020). "Unexpectedly, depletion of these cellular decay factors did not reproducibly rescue Pol II occupancy at the Fus and Rplp0 promoters during MHV68 infection compared to mock infected cells." (PMID 32032393, 2020).
gynecologic tumors (4 papers, 2016 to 2025). "Ribosomal P protein (RPLP0, RPLP1, RPLP2) expression was previously shown to correlate with invasiveness and metastasis in gynecologic tumors." (PMID 27741504, 2016).
adenocarcinoma (2 papers, 2007 to 2010). A common cancer characterized by the presence of malignant glandular cells. "Similarly, in adenocarcinomas of the colon, the expression of RPLP0, RPS14 and GAPDH varied between primary tumors and corresponding resection margins." (PMID 17640361, 2007).
neurodegenerative disease (1 paper, 2022). A disorder of the central nervous system characterized by gradual and progressive loss of neural tissue and neurologic function. "RPLP0 also modulates a variety of cellular functions in neurodegenerative diseases." (PMID 35342398, 2022).
neurological disorders (1 paper, 2006). "Our analysis revealed that the human RPS4X, RPS15A, and RPLP0 genes are located in chromosomal regions linked to brain or neurological disorders, and brain regions were affected in the morphants for these genes." (PMID 17183665, 2006).
RPLP0 also shares sentences with these, for which no sentence is quoted: bipolar disorder (2 papers); clear cell renal cell carcinoma (2); COVID-19 (2); acute myeloid leukemia (1); Alzheimer disease (1); aniridia (1); B-cell lymphoma (1); Burkitt lymphoma (1); Charcot-Marie-Tooth disease type 2L (1); chronic lymphocytic leukemia (1); colorectal tumors (1); glioma (1); goiter (1); hepatocellular carcinoma (1); HIV-1 infection (1); infectious disease (1); influenza infection (1); leukemia (1); mixed germ cell tumor (1); myopia (1); Neonatal sepsis (1); neuropathy (1); non-small cell lung carcinoma (1); osteosarcoma (1); ovarian endometrioid adenocarcinoma (1); ovarian mucinous adenocarcinoma (1); papillary thyroid carcinoma (1); parasite (1); Parkinson disease (1); polycystic ovary syndrome (1).
A further 5 diseases each share a sentence with RPLP0 in 1 paper.